MEG3 (maternally expressed 3)
Diseases named in the same sentence as MEG3 in open-access papers (continued):
Sharing a sentence is not in itself a finding about the gene and the disease.
esophageal tumor (1 paper, 2022). "5-Aza-dc could decrease the DNA methylation level in the promoter region of the lncRNA MEG3, thereby inhibiting cell proliferation and invasion of esophageal tumor cells." (PMID 36012763, 2022).
Fibroadenoma (1 paper, 2021). A benign tumor of the breast characterized by the presence of stromal and epithelial elements. "In the fibroadenoma patients, the serum MEG3 level of GA+AA genotype carriers was significantly lower than that of the GG genotype." (PMID 34421993, 2021). "MEG3 was found to be substantially downregulated in BC patients relative to healthy controls and fibroadenoma patients in the current study." (PMID 34421993, 2021). "Likewise, the serum MEG3 level of GA+AA genotype carriers in the fibroadenoma group (n = 56) was significantly lower than that of the GG genotype (n = 64) (t = 2.803, p = 0.0231)." (PMID 34421993, 2021).
fibrosarcoma (1 paper, 2021). A malignant mesenchymal fibroblastic neoplasm affecting the soft tissue and bone. "Besides, MEG3 also promoted the phosphorylation of rapidly accelerated fibrosarcoma (Raf), mitogen-activated protein kinase kinase (MEK), and extracellular-signal-regulated kinase (ERK) proteins." (PMID 34238211, 2021).
Glucose intolerance (1 paper, 2022). Glucose intolerance (GI) can be defined as dysglycemia that comprises both prediabetes and diabetes. "Hepatic MEG3 knockdown by injecting si-MEG3 fragments via the tail vein twice a week for 10 weeks improved glucose intolerance and IR in HFD mice." (PMID 36555704, 2022).
gonadotroph adenomas (1 paper, 2020). "Traditionally, the DLK1/MEG3 locus plays a tumor suppressor role in human gonadotroph adenomas." (PMID 33472171, 2020).
Hepatic steatosis (1 paper, 2018). Steatosis is a term used to denote lipid accumulation within hepatocytes. "However, the mechanism underlying the role of MEG3 in EtOH-induced hepatic steatosis and apoptosis is inadequate." (PMID 29692724, 2018). "The MEG3/miR-let-7c-5p/NLRC5 axis functions as an important player in EtOH-induced hepatic steatosis and apoptosis." (PMID 29692724, 2018). "Taken together, our data indicate that the MEG3/miR-let-7c-5p/NLRC5 axis functions as an important player in EtOH-induced hepatic steatosis and apoptosis." (PMID 29692724, 2018). "Firstly, we investigated the effects of MEG3 on EtOH-induced hepatic steatosis." (PMID 29692724, 2018).
inflammatory skin disease (1 paper, 2019). Inflammatory skin disorders covers a broad category that includes many conditions ranging in severity, from mild itching to grave medical health complications These disorders are common in people of all ages and races. "Although there was a panel of reports related to Meg3-mediated inflammatory responses, the role and mechanism of Meg3 in inflammatory skin disease and UVB-related damage remained unclear." (PMID 31761787, 2019).
intrauterine growth restriction (1 paper, 2014). "Related to development, maternal cigarette smoking during pregnancy causes reduced birth weight, and expression of MEG3 is down-regulated in placentae with intrauterine growth restriction, as was observed in human bronchial epithelial cells treated with cigarette smoke condensate." (PMID 24906187, 2014).
kidney damage (1 paper, 2022). "Notably, silencing MEG3 resulted in the attenuation of kidney damage and dysfunction, suggesting an injurious function of MEG3 in this model." (PMID 35464484, 2022).
knee osteoarthritis (1 paper, 2018). "A maternally expressed lncRNA, which was named MEG3, was closely connected to inflammation-related diseases, for example knee osteoarthritis." (PMID 30086750, 2018). "It was also shown that MEG3 was down regulated and negatively correlated with VEGF expression levels in cartilage samples from knee osteoarthritis patients." (PMID 30086750, 2018).
lung tumor (1 paper, 2022). "A recent study concluded that the MEG3 rs4081134 polymorphism is associated with a reduced risk of lung tumors in northeast China." (PMID 36544907, 2022). "A year later, another group firstly genotype three polymorphisms (rs3087918, rs11160608, and rs7158663) in MEG3 and found that the wild-type homozygous GG of MEG3 rs3087918 might be associated with a decreased risk of lung tumors." (PMID 36544907, 2022). "MEG3 up-regulates the sensitivity of lung tumor cells to chemotherapy drugs." (PMID 36544907, 2022).
lupus (1 paper, 2024). "In contrast, our results are not in line with another study which showed that lncRNA MEG3 was significantly higher in BD patients in comparison to lupus patients and the control group." (PMID 38985298, 2024).
lupus nephritis (1 paper, 2023). Glomerulonephritis in the context of systemic lupus erythematosus. "In the first study, urinary levels of the lncRNA targets MEG3, ANRIL, and lnc-MGC were tested for the identification of lupus nephritis." (PMID 37511572, 2023). "We further explored the relation between urinary levels of the lncRNA targets MEG3, ANRIL, and lnc-MGC and the severity of lupus nephritis." (PMID 37511572, 2023). "With ROC curve analysis, however, the AUC of MEG3, ANRIL, and lnc-MGC for the identification of lupus nephritis was only 0.559 (p = 0.7), 0.710 (p = 0.14), and 0.597 (p = 0.5), respectively." (PMID 37511572, 2023). "Urinary lnc-MGC level was marginally elevated in lupus nephritis compared to the control group (1.37 [IQR 0.65–57.37] vs. 0.63 [IQR 0.25–1.40] copies, p = 0.053), while urinary MEG3 levels were similar (0.52 [IQR 0.13–2.01] vs. 1.05 [0.25–5.03] copies, p = 0.3)." (PMID 37511572, 2023). "In spite of these theoretical reasons, our results indicated that the differences in urinary MEG3, ANRIL, and MGC levels between lupus nephritis and healthy controls were modest, and no reliable cut-off value could be determined for diagnostic use." (PMID 37511572, 2023).
malignant glioma (1 paper, 2018). A grade III or grade IV glioma arising from the central nervous system. "MEG3 downregulation and miR-19a upregulation were reported in malignant glioma tissues and cell lines, and luciferase results verified the complementary binding between miR-19a and MEG3." (PMID 30217221, 2018).
metastatic cancer (1 paper, 2021). A carcinoma which has spread from the original site of growth to another anatomic site. "In split cancer cells, little MEG3 transcript in primary cancer cells and little LINC01133 transcript in metastatic cancer cells were detected." (PMID 34055623, 2021).
multiple endocrine neoplasia type 1 (1 paper, 2020). An autosomal dominant tumor predisposition syndrome caused by pathogenic variants in the MEN1 gene, characterized by an increased risk of tumors of the parathyroid glands, pituitary gland, and foregut neuroendocrine tumors (most commonly pancreatic islet cells). "MEG3, which is downregulated in multiple cancer cell lines, is epigenetically activated upon the methylation of histone H3 at lysine 4 (H3K4me3) by MEN1 (multiple endocrine neoplasia type 1), a component of the MLL complex that functions as a tumor suppressor." (PMID 33291485, 2020).
myeloid leukemia (1 paper, 2019). A clonal proliferation of myeloid cells and their precursors in the bone marrow, peripheral blood, and spleen. "MiR-21 was considered to be an important miRNA, which was frequently elevated in all types of myeloid leukemia, while lncRNA MEG3 inhibited proliferation of CML cells by sponging MiR-21." (PMID 31164492, 2019).
myeloid malignancies (1 paper, 2017). "Hypermethylation of the MEG3 promoter was correlated with decreased overall survival and is a prognostic marker in myeloid malignancies." (PMID 28407691, 2017). "MEG3 promoter methylation was also correlated with reduced overall survival, and could serve as a prognostic marker in myeloid malignancies." (PMID 28407691, 2017).
neuroendocrine carcinoma (1 paper, 2021). A malignant neuroendocrine neoplasm composed of cells containing secretory granules that stain positive for NSE and chromogranin. "In that study, the expression of HOX transcript antisense RNA (HOTAIR), maternally expressed 3 (MEG3), and prostate cancer antigen 3 (PCA3) has been found to be significantly lower in pulmonary carcinoids as compared with neuroendocrine carcinomas." (PMID 33641055, 2021).
ocular toxoplasmosis (1 paper, 2019). Ocular toxoplasmosis is an infection in the eye caused by the parasite, Toxoplasm a gondii. "In our results—obtained in human retinal Müller cells, which have direct relevance to ocular toxoplasmosis—LINC01105, BANCR, MIR17HG, MIR155HG, lnc-SGK1, MEG3, KCNQ1OT1, NEAT1, NeST, and MALAT1 were the most dysregulated lncRNAs with known immunologic activities." (PMID 31547203, 2019).
oligodendroglioma (1 paper, 2023). A well-differentiated (WHO grade II), diffusely infiltrating neuroglial tumor, typically located in the cerebral hemispheres. "Similarly, the fact that MEG3 expression is higher in Grade 3 patients might be causing a greater difference between MEG3 overexpressed or siRNA treated oligodendroglioma cells and their controls." (PMID 37525401, 2023). "In patient‐derived oligodendroglioma cells 5FU significantly decreased cell viability when MEG3 was suppressed." (PMID 37525401, 2023). "The suppression of MEG3 enhanced the sensitivity of oligodendroglioma cells to the 5FU drug." (PMID 37525401, 2023).
orchitis (1 paper, 2021). Inflammation of one or both testes due to viral or bacterial infections. "This study successfully elucidated the role and underlying mechanism of MEG3 in Leydig cells under LPS and revealed a novel regulatory signalling pathway that offers a certain degree of potential for orchitis treatment." (PMID 33639974, 2021). "Maternally expressed gene 3 (MEG3) exerts a crucial role in various human diseases, but under orchitis, the role and underlying molecular mechanism of MEG3 in Leydig cells remain unclear." (PMID 33639974, 2021). "Therefore, this study aimed to investigate the role and further dissect the underlying molecular mechanism of MEG3 in Leydig cells under orchitis." (PMID 33639974, 2021). "However, there is a lack of focus in the literature on the functional roles and underlying mechanism of MEG3 in Leydig cells under orchitis." (PMID 33639974, 2021). "This study revealed that MEG3 serves as a molecular sponge to absorb miR-93-5p, thus leading to elevation of PTEN expression in Leydig cells under LPS treatment, offering a theoretical basis on which to establish potential new treatment strategies for orchitis." (PMID 33639974, 2021). "Finally, this study revealed that MEG3 exerted its function via modulation of the miR-93-5p/PTEN pathway in Leydig cells under LPS, thus indicating the potential of this signalling pathway in treatment of orchitis." (PMID 33639974, 2021).
pneumonia (1 paper, 2021). An acute, acute and chronic, or chronic inflammation focally or diffusely affecting the lung parenchyma, caused by an infection in one or both of the lungs (by bacteria, viruses, fungi, or mycoplasma.). "Our experiment of ROC provided a high sensibility and specificity of MEG3, indicating that MEG3 might be applied as a diagnostic biomarker for discriminating severe pneumonia occurrence." (PMID 34558385, 2021). "Overall, the increased expression of MEG3 and the reduced levels of miR-29 c were identified in severe pneumonia." (PMID 34558385, 2021). "Nevertheless, the expression of MEG3 in severe pneumonia children as well as its possible application and mechanism are elusive." (PMID 34558385, 2021). "More importantly, the correlation findings documented the levels of MEG3 were closely associated with neutrophils, CRP, and PCT, punctuating the clinical significance of MEG3 in severe pneumonia." (PMID 34558385, 2021). "Our study aimed to evaluate the clinical implication and potential mechanism of MEG3 in severe pneumonia." (PMID 34558385, 2021). "Additionally, the molecular mechanism of MEG3 relative to the pathogenesis of severe pneumonia was investigated." (PMID 34558385, 2021). "Abnormal alteration of MEG3 could prominently discriminate severe pneumonia patients from healthy children." (PMID 34558385, 2021). "The prominent enhancement of MEG3 expression was verified in the severe pneumonia group in comparison with the expression of MEG3 in healthy groups, which propounded severe pneumonia might contribute to the obvious abundance of MEG3 expression (P < 0.001)." (PMID 34558385, 2021). "In this study, the raised expression of MEG3 was determined in severe pneumonia patients, implying the anomalously expressed MEG3 might modulate the course of pneumonia." (PMID 34558385, 2021). "By comparison, MEG3 might be an alternative biomarker for patients with severe pneumonia." (PMID 34558385, 2021). "MEG3 might play roles in the clinical management of severe pneumonia." (PMID 34558385, 2021). "Subsequently, the K-M curve propounded a worse overall survival in group with high MEG3 expression than in low MEG3 level group and this result was further verified by the analysis of multivariate Cox, which indicated MEG3 could serve as a promising marker in severe pneumonia independently." (PMID 34558385, 2021). "Significantly, there were close linear correlations between MEG3 and neutrophils (R = 0.772, P < 0.001), CRP (R = 0.634, P < 0.001), and PCT (R = 0.727, P < 0.001), highlighting that MEG3 had a high possibility as a promising biomarker in severe pneumonia." (PMID 34558385, 2021). "Elevated expression of MEG3 and reduced microRNA-29 c (miR-29 c) were evaluated in severe pneumonia children, and a negative relationship between MEG3 and miR-29 c was propounded." (PMID 34558385, 2021). "Moreover, there was a distinct negative proportionate between MEG3 and miR-29 c in patients with severe pneumonia (R = −0.797, P < 0.001)." (PMID 34558385, 2021).
retinal degeneration (1 paper, 2020). Degeneration of the retina. "Recently, the Maternally Expressed 3 (MEG3) was shown to be involved in the pathogenesis of light-induced retinal degeneration." (PMID 33537317, 2020). "MEG3 expression is significantly upregulated upon light insult whereas its silencing protects against light-induced retinal degeneration in vivo and in vitro by decreasing caspase 3/7 activity and proapoptotic protein (Bax) levels while upregulating antiapoptotic protein (Bcl-2) expression." (PMID 33537317, 2020).
seminoma (1 paper, 2018). A radiosensitive malignant germ cell tumor found in the testis (especially undescended), and extragonadal sites (anterior mediastinum and pineal gland). "Moreover, our findings confirmed a strong association between oligozoospermia and imprinting defects (herein, on H19/IGF2, MEG3/DLK1, and SNURF DMRs for oligozoospermic patients with or without seminoma)." (PMID 30340650, 2018).
Stillbirth (1 paper, 2021). Death of the fetus in utero after at least 22 weeks of gestation. "Hypermethylation or loss of expression of MEG3 and NESP55 has been observed in the products of conception of spontaneous abortions and stillbirths." (PMID 34068021, 2021).
testicular germ cell tumours (1 paper, 2020). "The competitive binding of MEG3 and miR‐1297 to the 3′‐UTR of PTEN regulates the progression of testicular germ cell tumours via the PTEN/PI3K/AKT pathway." (PMID 32436312, 2020).
Testicular torsion (1 paper, 2021). Testicular torsion is when the spermatic cord to a testicle twists, cutting off the blood supply. "In summary, our research indicates that MEG3 contributes to pyroptosis by regulating miR-29a and PTEN during testicular I/R, indicating that MEG3 may be a potential therapeutic target in testicular torsion." (PMID 34222244, 2021).
thalassemia (1 paper, 2025). An inherited blood disorder characterized by a decreased synthesis of one of the polypeptide chains that form hemoglobin. "Although direct studies on the link between MEG3, thalassemia, and gut microbiota are limited, MEG3 may play an important indirect role in the interaction between these factors by regulating systemic inflammation and erythroid cell growth and differentiation." (PMID 40177354, 2025). "In thalassemia, MEG3 may act as a hematopoietic regulatory factor, indirectly affecting the clinical manifestations of the disease." (PMID 40177354, 2025).
thyroid tumor (1 paper, 2024). A benign or malignant neoplasm affecting the thyroid gland. "The expression of MEG3 is slightly reduced in thyroid tumor samples and drastically reduced or abolished in thyroid tumor cell lines." (PMID 38920632, 2024).
tongue cancer (1 paper, 2017). A malignant neoplasm affecting the tongue. "Other lncRNAs that have been reported in oral cancer include MEG3, which was down-regulated in tongue cancer, and UCA1, which was up-regulated in tongue cancer." (PMID 28415559, 2017).
urothelial carcinoma (1 paper, 2014). A malignant neoplasm derived from the transitional epithelium of the urinary tract (urinary bladder, ureter, urethra, or renal pelvis). "Our data support the idea that the main cause of the prevalent downregulation of DLK1 and MEG3 in urothelial carcinoma is epigenetic silencing across the 14q32 imprinted gene cluster, resulting in the unusual concomitant inactivation of oppositely expressed and imprinted genes." (PMID 25741387, 2014). "The genes DLK1 and MEG3 within this cluster are tumor suppressor candidates in urothelial carcinoma due to their known functions in the regulation of cell growth and development." (PMID 25741387, 2014). "Unexpectedly, we found that expression of both DLK1 and MEG3 was strongly diminished in urothelial carcinoma tissues and cell lines." (PMID 25741387, 2014). "Thus, whereas copy numbers of the 14q region were variously increased or decreased in urothelial carcinoma tissues and cell lines, MEG3 and DLK1 expression was reduced in almost all urothelial cancer tissues and cell lines, irrespective of copy numbers." (PMID 25741387, 2014). "Indeed, MEG3 has recently been reported to become downregulated in the majority of urothelial carcinomas and to exert tumor-suppressive functions." (PMID 25741387, 2014). "In previous reports on other cancer types, either DLK1 or MEG3 was reported to become deregulated, but not both genes, as we observed in urothelial carcinoma." (PMID 25741387, 2014).